STAT3 (signal transducer and activator of transcription 3)
Diseases named in the same sentence as STAT3 in open-access papers (continued):
Sharing a sentence is not in itself a finding about the gene and the disease.
atherosclerosis (continued). "In atherosclerosis, antisense suppression of SOCS3 in APOE -/- mice exacerbated atheroma development, whereas adenovirus-mediated upregulation of SOCS3 in the same model suppressed plaque development, in association with reduction in STAT1 and STAT3-dependent gene expression." (PMID 36172348, 2022). "Genes involved in fluid shear stress and atherosclerosis include IL1β, TNF, MMP9, AKT1, and NOX4; genes associated with AGE-RAGE signaling pathway in diabetic complications include AKT1, IL1β, and NOX4; while genes associated with HIF signaling pathway contain STAT3, NOX4, NFκB, and MAPK1." (PMID 36192741, 2022). "Our results indicated that high-fat diet and balloon injury of the aorta could cause the occurrence of atherosclerosis and the atherosclerotic rabbit exhibited elevated JAK2 and STAT3 phosphorylation levels, suggesting that the JAK/STAT3 signaling pathway is activated during atherosclerosis." (PMID 32169038, 2020). "However, emerging natural inhibitors, such as tricin, are indirect STAT3 inhibitors that could be used to treat atherosclerosis and have fewer side effects than previously used inhibitors." (PMID 31588227, 2019). "Notably, STAT3 can be divided into nuclear STAT3 and mitochondrial STAT3 according to its translocation, and both are believed to play important roles in the development of atherosclerosis, including endothelial cell dysfunction, macrophage polarization, inflammation and immunity." (PMID 31588227, 2019). "Therefore, STAT3 may become a potent target to treat atherosclerosis via regulating the polarization of macrophages." (PMID 31588227, 2019). "These inhibitors inhibit the JAK2/STAT3 signaling pathway in a similar way, which indicates that they may function by suppressing immune and inflammatory responses during the development of atherosclerosis." (PMID 31588227, 2019). "Therefore, a therapeutic strategy targeting STAT3 activity may be beneficial in treating atherosclerosis." (PMID 19330073, 2008). "For example, STAT3, a transcription factor activated by inflammatory cytokines, was reported to increase GSDME expression in vascular endothelial cells during atherosclerosis." (PMID 41550939, 2025). "STAT3 and JAK2 are also involved in numerous cardiovascular diseases, including diabetic cardiomyopathy, atherosclerosis, pathological myocardial hypertrophy and fibrosis, and lipopolysaccharide-induced myocardial injury." (PMID 40361044, 2025). "The analysis also identified inflammation-related targets within lipid and atherosclerosis pathways, such as STAT3, MMP9, MMP1, and AKT1, emphasizing the role of chronic inflammation in atherosclerosis development." (PMID 39808649, 2025). "S1PR3 also plays a protective role in atherosclerosis by promoting endothelial cell migration and inhibiting the apoptosis of macrophages through PI3K/AKT and STAT3/Survivin signals, respectively." (PMID 40092491, 2025). "Given the pivotal role of this phenotypic switch in the pathogenesis of atherosclerosis, it is crucial to identify effective therapeutic agents that target the JAK2/STAT3/KLF4 pathway to inhibit the transition of VSMCs to macrophage-like cells." (PMID 39062998, 2024). "The transcription factors RUNX1, GATA1, STAT3, NFκB, and PPAR have been widely reported to play key roles in the pathophysiology of platelet hyper-reactivity, thrombosis, and atherosclerosis." (PMID 36969155, 2023). "LOX-1 and oxLDL are fundamental in atherosclerosis, where oxLDL/LOX1 promotes ROS generation and NF-κB activation inducing the expression of IL-6, a STAT3 activator." (PMID 36982155, 2023).
atherosclerosis (continued). "SIN mainly affected 5 target genes, NFκB-1, TNF, interleukin 6, interleukin 1β and signal transducer and activator of transcription 3, and IL-17, AGE-RAGE signaling pathways, lipids, and atherosclerosis were all controlled to achieve therapeutic effects." (PMID 38206710, 2023). "Collectively, these data indicate the significance of STAT3 in GSDME transcriptional regulation, implying a possible therapeutic approach for atherosclerosis." (PMID 36807553, 2023). "In the model of atherosclerotic rabbits, the phosphorylation levels of JAK2 and STAT3 were increased, and the expression of SOCS3 was also upregulated, indicating that inhibition of JAK2/STAT3/SOCS3 signaling can alleviate atherosclerosis." (PMID 37089432, 2023). "The activation of NLRP3 was regulated by PI3K or AKT in atherosclerosis, and MAPK/NLRP3 inflammasome/STAT3 signaling was involved in the neuroinflammatory responses." (PMID 35457254, 2022). "The silencing of ROR ameliorates atherosclerosis progression by the inhibition of miR-26, NF-κB and JAK1/STAT3 signaling." (PMID 35407662, 2022). "Using immunofluorescence, expression of p-STAT3 was also repressed by IL-1β in CD68 + αSMA + cells, which were shown to accumulate in the plaque during atherosclerosis progression." (PMID 36456628, 2022). "IL-10 has a potential protective role in atherosclerosis and can be produced by macrophages and inhibits pro-inflammatory cytokine expression through a JAK/STAT3 dependent pathway." (PMID 34445361, 2021). "STAT3 has a well-known role in inflammation and immunity, and IL-1R signaling in CD4+ T-cells promotes Th17 immunity and atherosclerosis." (PMID 34630400, 2021). "Collectively, our data indicated that lnc-KCNC3-3:1 silencing inhibited the progression of atherosclerosis via inactivation of PI3K/Akt and JAK1/STAT3 signaling pathways." (PMID 34540913, 2021). "The signal transducer and activator of transcription 3 (STAT3), belonging to the STAT family, is conserved in structure and plays an important role in the process of atherosclerosis." (PMID 34688276, 2021). "Inhibition of STAT3 activation can prevent the VSMC contractile phenotype from switching to the inflammatory phenotype, eventually slowing the progression of atherosclerosis." (PMID 31588227, 2019). "Our results indicated that atherosclerotic mouse aortas exhibited elevated STAT3 phosphorylation levels and reduced IκBα levels, suggesting that the JAK/STAT3 signalling pathway and NF-κB pathway are activated during atherosclerosis." (PMID 27845432, 2016). "Previously, we have shown that, analogous to this study, AAV/STAT3 gene delivery, with STAT3 being down-stream of interleukin 10 (IL10), is similarly able to substitute for IL10, again, for inhibiting atherosclerosis." (PMID 25236373, 2014). "In a study we included, it was shown that Sal B could exert anti-inflammatory activity by inhibiting the STAT3/NF-κB signalling pathway and suppressing the expression of the inflammatory factors IL-1β, IL-6, and TNF-α, thereby attenuating atherosclerosis." (PMID 40606622, 2025). "Furthermore, silencing endogenous STAT3 reduced GSDME expression, further suggesting a potential therapeutic approach for atherosclerosis." (PMID 41550939, 2025). "The JAK2/STAT3 pathway promotes macrophage polarization toward the M1 phenotype, increasing the production of inflammatory molecules such as tumor necrosis factor‐alpha (TNF‐α), thereby accelerating the development of atherosclerosis." (PMID 40166646, 2025).
atherosclerosis (continued). "The JAK2/STAT3 signaling pathway is a classical inflammatory signaling pathway that regulates macrophage polarity toward the M1 phenotype and modulates the secretion of inflammatory factors (e.g., TNF-α), which exacerbates the course of atherosclerosis." (PMID 40647133, 2025). "Our findings provide, for the first time, novel evidence that quercetin suppresses the phenotypic switch of VSMCs to macrophage-like cells by inhibiting the JAK2/STAT3 pathway and reducing KLF4 expression, thereby preventing foam cell formation and attenuating atherosclerosis." (PMID 39062998, 2024). "In addition, CD36, JAK2, STAT3, and CDC42 are essential in reducing lipid accumulation and atherosclerosis in foam cells." (PMID 36903257, 2023). "A literature review revealed that flavanones could inhibit the IL6/JAK/STAT3/SOCS3 signaling pathway and improve atherosclerosis." (PMID 35799780, 2022). "Sustained expression of Ref‐1 and CRP accumulation in the cytosol may inhibit STAT3/Ref‐1 interactions and increase the inflammatory response of CRP, thus accelerating atherosclerosis after radiotherapy." (PMID 35178859, 2022). "Whereas, the inhibitor of the JAK/STAT3 pathway, such as protein inhibitor of activated STAT-3 (PIAS3), may be a critical repressor of atherosclerosis." (PMID 32283795, 2020). "Furthermore, we found that JAK2 and STAT3 phosphorylation were up-regulated in rabbits with atherosclerosis when compared with those of the control group, followed by the expression of SOCS3 was also increased due to the activation of JAK2 and STAT3." (PMID 32169038, 2020). "Although atherosclerosis is considered the critical pathological basis of most cardiovascular and cerebrovascular diseases, no specific reviews are aimed at the emerging roles of STAT3 in atherosclerosis." (PMID 31588227, 2019). "Additionally, mitochondrial STAT3 is a regulator of ETC and Ca2+ homeostasis and affects the mitochondrial production of ATP and ROS, thus playing a crucial role in atherosclerosis." (PMID 31588227, 2019). "In addition to STAT3, other STATs, especially STAT1 and STAT2, also play essential roles in atherosclerosis." (PMID 31588227, 2019). "Thus, mitochondrial STAT3 can sustain prolonged cytokine production and contribute to the differentiation of CD4+ T cells in atherosclerosis." (PMID 31588227, 2019). "It is conceivable that this pathway may be involved in the pathogenesis of ED, which frequently complicates atherosclerosis and deregulates the PDGFR/STAT3 pathway, and might contribute to clinical ED therapy." (PMID 28245285, 2017). "The raised inflammatory milieu driven by VSMCPCSK9-EVs was confirmed by the protein expression of phosphorylated form of STAT3 (signal transducer and activator of transcription 3) and SOCS3 (suppressor of cytokine signaling-3), two well-known cell signalling pathways involved in atherosclerosis." (PMID 36361853, 2022). "STAT3 positively regulates the expression of CX3CL1, and then down-regulates the inhibition of CX3CL1 by over-expression of miR-15a-5p, thus forming an elimination feedback loop to control the proliferation of HUVECs and affect the progression of atherosclerosis." (PMID 33456354, 2021). "Considering the important role of JAK2/STAT3/SOCS3 signaling pathway played in the inflammatory process in atherosclerosis, the potentially therapeutic strategy may be expected for the treatment of patients with atherosclerosis." (PMID 32169038, 2020). "Additionally, most inhibitors targeting the SH2 domain are not STAT3-specific, which makes it difficult to rule out the roles of other STATs in atherosclerosis." (PMID 31588227, 2019). "Together, these data suggest that M2 macrophage-specific targeting of STAT3 signalling pathway may lead to novel therapies to treat CNV in AMD and potentially other diseases such as atherosclerosis and cancers where abnormal proliferative angiogenesis is pathogenic." (PMID 26260587, 2015).
atherosclerosis (continued). "Moreover, the newly identified mechanism by which flavonoids (naringenin and flavone) inhibit STAT3 may provide an avenue for developing novel therapies for atherosclerosis based on the induction of negative STAT3 regulators." (PMID 31588227, 2019). "Indeed, our results demonstrate hyperphosphorylation of both AMPK and JAK2/STAT3 signalling through MSI-1436 in acute oxLDL-challenge, which may result in a more favourable inflammatory phenotype and make beneficial effects of the compound in early atherosclerosis feasible." (PMID 37828508, 2023). "However, whether ruxolitinib plays a key role in atherosclerosis process and JAK2/STAT3/SOCS3 signaling pathway is still not well understood." (PMID 32169038, 2020).
cardiac hypertrophy (138 papers, 2009 to 2025). "We took advantage of this well characterized model of cardiac hypertrophy to assess the role of MEF2A and STAT3 in this cellular process since both proteins have been previously independently implicated in cardiac hypertrophy." (PMID 37019881, 2023). "The role of BMX gene silencing is to inhibit downstream STAT3 signaling which is an important cardioprotective factor associated with cardiac hypertrophy." (PMID 35296647, 2022). "STAT3 activation is an important cardioprotective factor associated with cardiac hypertrophy, and the role of BMX gene silencing is to inhibit downstream STAT3 signaling." (PMID 35296647, 2022). "Modern studies have shown that JAK2/STAT3 signaling pathway activation is associated with cardiac hypertrophy; it is one of the important pathways of cardiac apoptosis and is of great significance in cardiomyocyte signal transduction pathways." (PMID 34221090, 2021). "In the recent study, chrysophanol, the aglycone of C8G, was reported to block STAT3 signaling pathways associated with cardiac hypertrophy; however, to the best of our knowledge, this is the first study to show the effects of C8G on STAT3 signaling pathway." (PMID 33261209, 2020). "Serine 727 (Ser727) phosphorylation has a primary part in STAT3 influence on mitochondria: its decrement is associated with the development of cardiac hypertrophy and dilated cardiomyopathy." (PMID 30622968, 2018). "Granted many of these studies are also less than definitive as they base their conclusions on an association of STAT3 activity levels with cardiac hypertrophy and/or use a pharmacological inhibitor." (PMID 30619368, 2018). "Third, the underlying mechanism by which HSF1 attenuated ischaemia‐induced cardiac hypertrophy is associated with the blockage of the JAK2/STAT3 pathway." (PMID 29992755, 2018). "Earlier studies revealed that global reduction of STAT3 activity reduced cardiac hypertrophy with hypertension, but caused a disruption of myofilaments and increased contractile dysfunction." (PMID 30619368, 2018). "The original suspicion that STAT3 was positively linked to cardiac hypertrophy arose from observations that several members of the IL-6 family of cytokines induced growth of isolated neonatal rat ventricular myocytes." (PMID 30619368, 2018). "Moreover, CPT1b overexpression decreased L-carnitine levels and inhibited the Jak2/Stat3 signaling pathway, which was associated with the pathogenesis of myocardial hypertrophy." (PMID 40093901, 2025). "In particular, we have documented an interaction between MEF2A and STAT3 that may balance the regulation of critical gene networks associated with the inflammatory response, cardiomyocyte cell survival and cardiac hypertrophy." (PMID 37019881, 2023). "There is evidence to show the association between AT1R/STAT3 and cardiac hypertrophy progression." (PMID 35662276, 2022). "In addition, C/EBPδ protein levels can be induced by IL-6 and mediated by STAT3 in cardiomyocytes, leading to cardiac hypertrophy which can cause cardiac fibrosis through multiple mechanisms." (PMID 36299447, 2022). "According to these results, we speculate that TRIM10‐mediated pathological cardiac hypertrophy may be associated with AKT‐ or STAT3‐dependent signalling." (PMID 32343488, 2020). "In addition, over-expression of STAT3 in mouse cardiomyocytes caused cardiac hypertrophy by increasing expression of hypertrophic genes (ANF, MHC, CT-1)." (PMID 31709266, 2019). "The inactivation of STAT3 resulting from the loss of gp130 may be a key event in the transition from cardiac hypertrophy to heart failure." (PMID 31709266, 2019). "However, an earlier study that infused AngII into mice with a global S727A mutation that impedes STAT3 activation showed reduced cardiac hypertrophy and increased reparative patches of fibrosis in the heart." (PMID 30619368, 2018). "Moreover, STAT3 deficiency promoted a shift toward increased glucose utilization with cardiac hypertrophy." (PMID 30619368, 2018).